PABPC1 (poly(A) binding protein cytoplasmic 1)
Diseases named in the same sentence as PABPC1 in open-access papers (continued):
Sharing a sentence is not in itself a finding about the gene and the disease.
infection (continued). "PABPC1 indeed re-localizes into the nucleus during lytic infection, and the subnuclear distribution of PAN RNA and of re-localized PABPC1 appear strikingly similar." (PMID 22022268, 2011). "Importantly, we also demonstrate that increasing PABPC1 levels during infection rescues the degradation of host mRNAs, consistent with additional PABPC1 becoming available to bind short poly(A)-tailed transcripts." (PMID 41279592, 2025). "Among these dsRNA-positive cells, 34% (209/604) of the rH234-infected cells exhibited PABPC1 nuclear accumulation, which is roughly threefold higher than the 13% observed in rWT-infected cells (128/1,005, P < 0.0001), suggesting rH234A infection triggering a stronger RNase L activation." (PMID 40838727, 2025). "The results showed that overexpression of PABPC1 enhanced host mRNA translation (lanes 1 and 3), but this enhancement was suppressed upon EV-D68 infection (lanes 3 and 4), although it remained higher than in the control group without PABPC1 transfection (lanes 2 and 4)." (PMID 40294010, 2025). "PABPC1 activity is limiting during infection, which destabilizes short-tailed host mRNAs." (PMID 41279592, 2025). "Consistent with the lack of PA-X host shutoff protein, B/Bris/60 infection did not cause nuclear PABPC1 accumulation." (PMID 38629840, 2024). "Conversely, overexpression of PABPC1 increased infection load in A549 cells." (PMID 39334466, 2024). "Surprisingly, we found that vhs-GFP exhibited little if any endoribonuclease activity despite functioning in isolation and maintaining its physical characteristics during infection, a result that was backed up by the failure of PABPC1 to relocalize to the nucleus." (PMID 35758691, 2022). "In uninfected cells, PABPC1 has a steady-state cytoplasmic localization, however upon infection with HSV-1, or expression of vhs by transient transfection, PABPC1 accumulates in the nucleus in a vhs-dependant manner, meaning that relative PABPC1 localization is a useful surrogate for vhs function." (PMID 35758691, 2022). "In our previous studies about transcription analysis of immortalized porcine intestinal epithelial cell clone J2 (IPEC-J2) cells after PEDV infection, we found that the mRNA expression of the PABPC1 gene significantly up-related at 12–18 h post infection (hpi)." (PMID 35746667, 2022). "Moreover, PABPC1 plays an important role in the infection and replication of the influenza virus, porcine reproductive and respiratory syndrome virus, and Rift Valley fever virus." (PMID 33499896, 2021). "Our results showed that SVV infection resulted in the cleavage of PABPC1." (PMID 32512928, 2020). "The fact that PABPC1 binds to PAN RNA in the nucleus during a lytic infection could be indicative of the virus manipulating the host environment to favor the export and expression of viral mRNAs." (PMID 25375885, 2014). "The dramatic influx of PABPC1 into the nucleus during KSHV lytic infection might therefore perturb the process of mRNA nuclear export." (PMID 22022268, 2011). "Nuclear re-localization of PABPC1 is also observed during infection with Bunyamwera virus." (PMID 22022268, 2011). "However, infection with EndoU activity-deficiency mutant virus rIBV-nsp15-H238A results in the accumulation of viral dsRNA, triggering a PKR-eIF2α-dependent shutdown of protein synthesis and leading to the nuclear relocation of PABPC1." (PMID 40096172, 2025). "Given the fact that both PABPC1 and LARP1 have RNA-binding activity, one could envisage that RyDEN may associate with DENV RNA through its interaction with these proteins during infection." (PMID 26735137, 2016). "To explore the effects of PABPC1 and LARP1 on viral replication, we overexpressed PABPC1-Flag or LARP1-Flag in RD cells, followed by infection with EV-A71 or CV-A16." (PMID 40294010, 2025). "RD cells were transfected with PABPC1-Flag or LARP1-Flag plasmids, followed by infection with EV-D68, and the cells were collected for immunoblotting and viral titer analysis." (PMID 40294010, 2025).
infection (continued). "We find that infection with IBV with functional nsp15 suppresses protein synthesis in a PKR-eIF2α independent manner, with PABPC1 mainly located in the cytoplasm." (PMID 40096172, 2025). "Hereto, ICC analyses were performed at 7 days post-infection for 2 well-described protein components of stress granules (SGs), namely G3BP1 (G3BP stress granule assembly factor 1) and PABPC1 (poly(A) binding protein cytoplasmic 1)." (PMID 39351233, 2024). "In this study, we find that APOBEC3B forms a complex with PABPC1 to stimulate PKR and counterbalances the PKR-suppressing activity of ADAR1 in response to infection by many types of viruses." (PMID 36781883, 2023). "We therefore examined the relative compartmentalisation of PABPC1 in HFFF cells infected with Wt, Δvhs, Δ22 or rescue viruses at 10 and 16 hours after infection." (PMID 37343008, 2023). "To address how PAN RNA contributes to lytic infection of KSHV, we began by investigating protein components of the PAN RNP and identified poly(A)-binding protein C1 (PABPC1)." (PMID 22022268, 2011). "Infection of shIL2 expressing cells with the PR8 NS1(123,124A) mutant virus did not cause nuclear PABPC1 accumulation." (PMID 38629840, 2024). "Despite vhs-GFP maintaining activity when expressed in isolation, it failed to degrade mRNA or relocalise PABPC1 during infection, while viral transcript levels were similar to those seen for a vhs knockout virus." (PMID 35758691, 2022). "The most striking result from this study is that despite the lack of endoribonuclease activity and PABPC1 retention in the nucleus, vhs-GFP maintains the ability to cause the vhs-dependent nuclear retention of IE and E transcripts in WT infection." (PMID 35758691, 2022). "The functional interaction of RyDEN with cellular mRNA-binding proteins PABPC1 and LARP1 prompted us to test whether RyDEN was recruited to DENV RNA during infection." (PMID 26735137, 2016). "Interestingly, infection with this 229E nsp15 mutant resulted in activation of the OAS/RNase L pathway, as evidenced by total rRNA degradation in MRC-5 and HT1080 cells, as well as increased nuclear PABPC1 localization in MRC-5 cells." (PMID 41369222, 2026). "Notably, infection with either rWT or rH234A did not induce PABPC1 nuclear trafficking, indicating that virus-induced PABPC1 nuclear trafficking is RNase L-dependent." (PMID 40838727, 2025). "We also noticed that an average of 44% rWT- and 51% rH234A-infected cells show PABPC1 cytoplasmic puncta, although the percentages do not statistically differ between the two infections, consistent with the notion that PABPC1 cytoplasmic puncta formation can be RNase L-independent." (PMID 40838727, 2025). "Unlike eIF4G and PABPC1, eIF4E protein levels remained unchanged upon EV-D68 infection." (PMID 40294010, 2025). "This lack of stress-induced translational shutoff is further emphasized by the fact that, despite remaining cytoplasmic in HSV1 vhs-GFP infected cells, PABPC1 did not localize to cytoplasmic foci, suggesting that recruitment of mRNA into stress granules was not a feature of this infection." (PMID 35758691, 2022).
heart disease (1 paper, 2023). "When heart disease occurred, the poly(A) tail became longer and the expression level of PABPC1 increased." (PMID 37215497, 2023).
retinopathy (1 paper, 2024). "In GWAS analysis, we found 12 SNPs had a significant association (p < 10-4) with HCQ retinopathy in genes LCE4A, HRNR, OR2T4, NUDT17, CCDC66, PRSS3, PABPC1 and IGHV." (PMID 38548946, 2024).
PABPC1 also shares sentences with these, for which no sentence is quoted: Alzheimer disease (2 papers); Calicivirus infection (2); kidney disease (2); lung adenocarcinoma (2); neurodegenerative disease (2); renal cell carcinoma (2); acute myeloid leukemia (1); atherosclerosis (1); autism (1); brain ischemia (1); cardiovascular diseases (1); cerebral infarction (1); colon adenocarcinoma (1); diabetic retinopathy (1); diffuse large B-cell lymphoma (1); endometrial cancer (1); enterovirus infection (1); frontotemporal dementia (1); fungal infection (1); head and neck squamous cell carcinoma (1); heart failure (1); Hyperglycemia (1); hypertrophy (1); insulinoma (1); leukemia (1); liver cirrhosis (1); major depressive disorder (1); membranous nephropathy (1); multiple sclerosis (1); myelodysplastic syndrome (1).
A further 9 diseases each share a sentence with PABPC1 in 1 paper.